TFEB (transcription factor EB)
Diseases named in the same sentence as TFEB in open-access papers (continued):
Sharing a sentence is not in itself a finding about the gene and the disease.
infection (continued). "However, future studies are required to address whether or not SetA directly targets endogenous TFEB under infection conditions." (PMID 32622269, 2020). "CVB3 activates TFEB by inactivating mTORC1 signaling, promoting the non-lytic release of CVB3 via a secretory autophagic pathway during the early stages of infection." (PMID 41277866, 2026). "Our analysis showed that NHR-49/PPAR-α is not required for as large a portion of the host response to infection as HLH-30/TFEB, even though NHR-49/PPAR-α is partially required for HLH-30/TFEB induction." (PMID 33978570, 2021). "However, whether HLH-30/TFEB regulates the infection-specific response was not known." (PMID 33978570, 2021). "Interestingly, two teams recently reported that AMPK could dephosphorylate TFEB/TFE3, induce their nuclear localization independently of mTOR activity, and activate TFEB/TFE3 boost the expression of lysosomal and inflammatory genes in macrophages in response to infection." (PMID 33330475, 2020). "Leptomycin-B treatment inhibited transcription factor-EB, the master transcriptional regulator of autophagy translocation upon refeeding, as expected, but it did not obstruct SIRT-1 translocation induced by EV-D68 infection." (PMID 37850626, 2023).
metabolic disorders (18 papers, 2017 to 2025). "Taken together, our findings indicate that the loss of TFEB in PTECs causes metabolic disorders in aged mice." (PMID 39699959, 2024). "Further research is needed to examine the mechanism of the elevated plasma FFA levels and whether the metabolic disorders are also caused by the deficiency of TFEB in other segments, such as the S1/S2 segments." (PMID 39699959, 2024). "TFEB deficiency in PTECs leads to metabolic disorders in aged mice." (PMID 39699959, 2024). "Our data adds to a growing body of literature supporting a beneficial role for macrophage TFEB in metabolic disease." (PMID 41665896, 2025). "The activation of TFEB has further been demonstrated to have an advantageous impact on metabolic disorders." (PMID 40354374, 2025). "Activation of autophagy, via the transcription factor TFEB, is a promising strategy to treat metabolic diseases." (PMID 29273768, 2017). "Another study has highlighted the inhibitory effects of TFEB activation on metabolic disorders." (PMID 40354374, 2025). "In view of its function, TFEB activation, induced by nuclear receptor PPARα with currently available drugs or new molecules, might be a therapeutic target for the treatment of metabolic diseases." (PMID 36670934, 2022). "Combined therapeutic approaches targeting TFEB and mTORC1 with intermittent fasting could be a rewarding direction in the intervention of T2D and other metabolic disorders." (PMID 30710421, 2019). "Consequently, TFEB/TFE3 agonists are of interest for potential therapeutic intervention for some metabolic disorders and/or ageing." (PMID 29273768, 2017).
kidney disease (14 papers, 2020 to 2025). "Indeed, TFEB overexpression improves the phenotypes associated with various diseases characterized by autophagy defects, including kidney diseases and cardiac hypertrophy." (PMID 37188688, 2023). "In summary, we have discovered that TFEB plays a fundamental role in the development of kidney disease downstream of Tsc2 knockdown in two distinct mouse models of TSC." (PMID 38195686, 2024). "Knockout of TFEB rescues kidney pathology and overall survival, indicating that TFEB is the primary driver of renal disease in TSC." (PMID 38195686, 2024). "Here, the authors show that TFEB is the primary driver of renal disease and mTORC1 hyperactivation in TSC." (PMID 38195686, 2024). "TFEB is also considered to be a therapeutic target in kidney diseases, and we have clarified that TFEB in PTECs protects against kidney injury by maintaining lysosomal homeostasis." (PMID 39699959, 2024). "Our data reveal for the first time that TFEB is the critical driver of renal disease in two mouse models of TSC." (PMID 38195686, 2024). "In contrast, inhibition of the cytosolic deacetylase, HDAC6, enhances TFEB acetylation, which in turn increases TFEB nuclear localization in experimental kidney disease, but the deacetylation site on TFEB and the exact mechanisms behind this are still unclear." (PMID 36184826, 2023). "Taken together, this highlights the importance of developing novel therapeutic strategies against kidney diseases based on TFEB regulation." (PMID 32377395, 2020). "We have emphasised the role of TFEB in kidney diseases and its potential as a therapeutic in rescuing renal function." (PMID 32377395, 2020). "In this review, we present an overview of the current data on TFEB and its implication in kidney disease." (PMID 32377395, 2020). "Thus, pharmacological approaches to modulate autophagy focused on TFEB hold promise for treating kidney diseases." (PMID 39949488, 2025). "Collectively, these results suggest that TFEB may be involved in the regulation of autophagy and fibrosis and that regulating TFEB activity may be a promising therapeutic strategy against kidney diseases." (PMID 35897713, 2022). "Collectively, our results suggest that TFEB may be involved in the regulation of autophagy and fibrosis and that regulating TFEB activity may be a promising therapeutic strategy against kidney diseases." (PMID 35897713, 2022). "Therefore, further studies need to be performed to develop TFEB as a therapeutic target for kidney diseases." (PMID 32377395, 2020). "However, the function and mechanism of TFEB involved in the treatment process of kidney disease are still notemployed by TFEB in these processes remain to be fully understood." (PMID 32377395, 2020). "Regulating TFEB activity may be a promising therapeutic strategy against kidney diseases." (PMID 32377395, 2020). "The evidence that kidney-specific knockout of TFEB has no detectable effects on kidney physiology suggests that targeting TFEB could represent an alternative and potentially safer therapeutic strategy for TSC-associated renal disease, and potentially for other TSC-associated manifestations." (PMID 38195686, 2024).
bacterial infection (10 papers, 2017 to 2025). "Therefore, TFEB is associated with host defense against bacterial infection." (PMID 32528902, 2020). "Macrophages deficient in TFEB and TFE3 fail to adopt a pro‐inflammatory phenotype in response to bacterial infection." (PMID 39439196, 2025). "Collectively, our data indicate that BDQ activates TFEB in macrophages and in this way modulates innate immune resistance to bacterial infection." (PMID 32369020, 2020). "To explore the activity of TFEB under bacterial infection with the treatment of inhibitors, we isolated the cytoplasm and nucleus of BMDMs to check the level of TFEB." (PMID 33324360, 2020). "Previous reports have shown that HLH-30/TFEB is nuclear localized upon bacterial infection and is required for activation of autophagy and anti-microbial gene transcription in C. elegans." (PMID 30190478, 2018). "Because TFEB plays an essential role in the colon under bacterial infection and the majority of research focuses on macrophages, we were eager to explore the detailed distribution of TFEB, which might clarify the TFEB-mediated anti-bacterial responses." (PMID 38711975, 2024). "Interestingly, TFEB siRNA- and pEGFP-N1-TFEB-transfected A549 cells prolonged the significant reduction and increase of the A. baumannii persistence inside A549 cells during 8 h of bacterial infection by 2.95 and 1.17 log CFU/ml compared with control cells, respectively." (PMID 29600279, 2018). "Briefly, RAW cells were treated with cigarette smoke extract (CSE), chloroquine (autophagy inhibitor), TFEB-shRNA, CFTR(inh)-172, and/or fisetin prior to bacterial infection for functional analysis." (PMID 29445254, 2017). "Additionally, a recent study has demonstrated that TFEB can also stimulate IRG1 expression and itaconate production during bacterial infection in macrophages." (PMID 39349845, 2024). "Previous studies have shown that TFEB/HLH-30 localizes predominantly in the cytoplasm in basal conditions and translocates into the nucleus upon several cellular stresses, such as lysosomal impairment, bacterial infection, prolonged ER stress, and nutrient scarcity." (PMID 30299269, 2018).
cardiovascular diseases (8 papers, 2018 to 2025). "Numerous studies indicate that mutations or dysfunctions of TFEB SUMOylation sites, as vital regulatory mechanisms, are closely associated with lipid metabolism in cardiovascular disease." (PMID 41516224, 2025). "Altered TFEB gene expression and subsequent dysfunctional autophagic-lysosomal system have been implicated in human diseases, including cardiovascular diseases." (PMID 33732699, 2021). "Indeed, recent studies have linked TFEB SUMOylation with cardiovascular disease." (PMID 41516224, 2025). "SUMOylation has been shown to exert a complex effect on TFEB activity, thereby influencing lipid metabolism in cardiovascular disease." (PMID 41516224, 2025). "TFEB can upregulate the expression of nearly two-thirds of autophagy–lysosome genes and its overexpression shows potential therapeutic effects in cardiovascular disease by rescuing lipid-induced lysosomal dysfunction as well as enhancing lipolysis." (PMID 30046966, 2018). "Abnormal SUMOylation may cause changes in subcellular localization and the stability and transcriptional activity of TFEB proteins, ultimately leading to cardiovascular disease, metabolic disease, neurodegenerative disease, and tumors." (PMID 41516224, 2025). "Transcription factor EB (TFEB), which regulates major proteins and molecules in signaling pathways through nuclear translocation, is considered a potential target for the development of new therapies for cardiovascular diseases." (PMID 41516224, 2025). "Therefore, disturbances or decreases in TFEB activity can lead to the onset and progression of various cardiovascular diseases." (PMID 41516224, 2025). "However, how to pharmacologically activate TFEB to protect against cardiovascular diseases remains largely unknown." (PMID 35228523, 2022). "Therefore, this review highlights recent research findings on the regulation of TFEB SUMOylation in lipid metabolism and its related molecular mechanisms to provide insights and a theoretical basis for developing potential novel therapeutics for related cardiovascular diseases." (PMID 41516224, 2025). "Thus, altered TFEB level may contribute to cardiovascular diseases." (PMID 33732699, 2021).
neurological diseases (5 papers, 2016 to 2025). "According to that study, the deficiency of TDP-43, a hallmark protein broadly involved in diverse neurological disorders, can lead to neurotoxicity through the enhancement of TFEB-mediated biogenesis of autophagosomes and lysosomes, and the blocking of the autophagosomal and lysosomal fusion." (PMID 37745295, 2023). "The therapeutic potential of melatonin as an inducer of autophagy via TFEB activation has been proposed in models of nervous system diseases." (PMID 39940940, 2025). "Targeted TFEB therapy has shown potential in addressing autophagy dysfunction in neurological diseases." (PMID 39940940, 2025).
immune disorder (4 papers, 2021 to 2024). "We highlight TFEB and TFE3 as a potential therapeutic target to regulate the ALP and immune dysfunction in DCs caused by As exposure." (PMID 38267572, 2024). "TRIM18 targets PP2A for proteasomal degradation and inhibits TFEB dephosphorylation and nuclear translocation, leading to autophagy inhibition and the development of an immune disorder." (PMID 34434118, 2021). "Fucoidan could maintain pancreatic homeostasis and restore immune disorder through enhancing autophagy via the AMPK/mTOR1/TFEB pathway in pancreatic cells." (PMID 38164477, 2024). "In summary, our study confirmed that TFEB and TFE3 activated ALP and therefore may exert a collaboratively protective effect on As-induced immune dysfunction in DCs." (PMID 38267572, 2024).
cerebral artery (3 papers, 2018 to 2023). "Although some researchers have proposed that lactic acid in TAM can activate mTORC1 signal and thereby inhibit TFEB-mediated ATP6V0D2 expression, our data show that ATP6V0D2 reduces liver IR injury mainly by inducing autophagolysosome formation, without significant activation of Notch signal." (PMID 33860063, 2021).
retinopathy (2 papers, 2023). "Upregulating TFEB-mediated activation of lysosomal gene transcription to reduce the potential danger of CQ-induced retinopathy would likely promote the biogenesis of lysosomes with the same impaired ability to reform as the preexisting lysosomes." (PMID 37548963, 2023).
animal disease (1 paper, 2021). "Activation of TFEB with pharmacological agents has been shown to confer beneficial effects in various cellular and animal disease models." (PMID 33995096, 2021).
central nervous system diseases (1 paper, 2025). "It has been fully confirmed that TFEB may be an endogenous protective factor in central nervous system diseases." (PMID 40324256, 2025).
inflammation (1 paper, 2018). Aberrant reaction of the microcirculation characterized by movement of fluid and leukocytes from the blood into extravascular tissues. "Finally, the protective effect of CO against LPS/D-GalN-induced acute hepatic inflammation in mice is likely related to mitochondrial quality control which is dependent on both TFEB-mediated mitophagy and mitochondrial biogenesis." (PMID 30333475, 2018).
myopathy (1 paper, 2022). A disease of the muscle in which the muscle fibers do not function properly. "Moreover, Vcp knockout in mouse muscles induces a necrotic myopathy with damaged lysosomes and LGALS3 upregulation, inducing autophagy via transcription factor EB (TFEB) activation." (PMID 35501124, 2022).
vascular disorder (1 paper, 2019). A general term used to describe any disease affecting blood vessels]. "Our data suggest that suppression of TFEB may be an initiating mechanism that promotes SMC dedifferentiation leading to accelerated neointima formation in vascular disorders associated with metabolic stress, whereas trehalose reverses these changes." (PMID 31515484, 2019).
TFEB also shares sentences with these, for which no sentence is quoted: Parkinson’s (6 papers); cholangiocarcinoma (5); dilated cardiomyopathy (3); Fabry disease (3); hyperlipidemia (3); oncocytic tumour (3); oncocytoma (3); renal medullary carcinoma (3); translocation renal cell carcinoma (3); Age-Related Hearing Loss (2); alcohol (2); Arthritis (2); brain tumor (2); cardiac arrhythmias (2); cardiac diseases (2); chronic liver failure (2); clear cell renal carcinoma (2); cutaneous squamous cell carcinoma (2); Duchenne muscular dystrophy (2); frontotemporal dementia (2); memory (2); papillary renal cell carcinoma (2); abdominal aortic aneurysm (1); acute myocardial infarction (1); adenocarcinoma (1); alcoholic liver diseases (1); astrocytoma (1); brain diseases (1); bronchopulmonary dysplasia (1); Cirrhosis (1).
A further 54 diseases each share a sentence with TFEB in 1 paper.